C6orf118 (chromosome 6 open reading frame 118)
Synonyms: MGC23884; bA85G2.1; dJ416F21.2
Tractability: No criterion of Open Targets' tractability assessment is met for any kind of drug.
Gene: Protein-coding gene on chromosome 6 (165,279,664 to 165,309,605, reverse strand). Ensembl gene ENSG00000112539.
Subcellular location (Human Protein Atlas): Mitochondria
Genetic constraint (gnomAD): Loss-of-function variants: 40 observed, 40.42 expected, observed/expected ratio (o/e) 0.99, 90% interval 0.77 to 1.29. The upper end of that interval is the gene's LOEUF score, 1.29, which puts it in group 5 of 6, group 1 being the genes least tolerant of losing a copy. Missense variants: 591 observed, 544.07 expected, observed/expected ratio (o/e) 1.09, 90% interval 1.01 to 1.16. Synonymous variants: 226 observed, 223.47 expected, observed/expected ratio (o/e) 1.01, 90% interval 0.91 to 1.13.
Homologues: Orthologues: chimpanzee C6H6orf118 (93% identical), macaque C4H6orf118 (87% identical), dog C6orf118 (64% identical), rat MGC94891 (58% identical), guinea pig C6orf118 (57% identical), mouse 1700010I14Rik (54% identical), tropical clawed frog c5h6orf118 (27% identical).